IL6 (interleukin 6)
Diseases named in the same sentence as IL6 in open-access papers (continued):
Sharing a sentence is not in itself a finding about the gene and the disease.
cardiovascular disease (continued). "Therefore, some studies suggested that IL-6 is a biomarker with better sensitivity and characteristics than CRP for the diagnosis of cardiovascular disease." (PMID 34542791, 2021). "Among uninfected ambulatory adults without cardiovascular disease, RDW was associated with elevated pro-inflammatory cytokines (TNF-α, IL8, IL6, IL1b), but not regulatory cytokines (TGFb)." (PMID 33089037, 2020). "The primary adipokines that play a role in inflammation, metabolic and cardiovascular diseases include adiponectin, leptin, resistin, visfatin, tumor necrosis factor alpha (TNF-α), interleukin-6(IL-6), plasminogen activator inhibitor-1 (PAI-1), and vascular endothelial growth factor (VEGF)." (PMID 33050331, 2020). "Additionally, LncRNA RP5-833A20.1 has also been reported to elevate the levels of inflammatory factors, such as IL-1β, IL-6, and, TNF-α in THP-1 macrophages in cardiovascular disease." (PMID 32629426, 2020). "In contrast to this lack of influence from post-BD-AO, serum IL-6 was found to act on cardiovascular risk, which is consistent with IL-6 being on the causal pathway between NO2 and cardiovascular disease." (PMID 28481326, 2017). "After excluding participants with cardiovascular disease, IL-6 and CRP levels were still not found elevated in impaired cognitive function patients compared to healthy controls." (PMID 28798686, 2017). "The most extensively studied biomarkers of inflammation in cardiovascular disease are CRP and IL-6." (PMID 24782595, 2014). "Also, we did not measure other markers of systemic inflammation that have been shown to correlate with cardiovascular disease in HIV, such as IL-6." (PMID 24586854, 2014). "Joint relationship between IL-6, D-dimer and hs-CRP, D-dimer with cardiovascular disease (CVD)." (PMID 22970224, 2012). "Although it is outside the scope of this review to detail all potential roles of IL-6 (or its downstream product, C-reactive protein (CRP)) as a cardiovascular biomarker in different cardiovascular diseases, it is important to emphasize that elevation of IL-6 is associated with diverse pathologies." (PMID 19936194, 2008). "These multiple actions indicate that IL-6 is not merely a passive biomarker, but actively modulates responses to cardiovascular disease." (PMID 19936194, 2008). "Circulating IL-6 concentrations also predict cardiovascular disease in the general population, independent of hs-CRP levels." (PMID 15899050, 2005). "Additionally, the study's population consists of individuals without known cardiovascular diseases, which reduces confounding variables and allows for a more focused analysis of suPAR and IL‐6." (PMID 40619914, 2025). "This prospective study assessed the long‐term prognostic value of suPAR, IL‐6, and their combination regarding all‐cause mortality and MACE in a large (n = 962) population of individuals with T1D without known cardiovascular diseases from the Capital Region of Denmark." (PMID 40619914, 2025). "We demonstrated that the TG/HDL ratio, IL-2, IL-6, IL-17A, and INF-γ were significantly greater in subjects with MetS than in those without MetS, and may therefore be used as biomarkers to predict future cardiovascular disease." (PMID 37892418, 2023). "Study participants had T2DM with no history of inflammatory diseases, cardiovascular diseases, medication and/or any health condition that might affect the inflammatory markers, interleukin 6 (IL-6) and C-reactive protein (CRP)." (PMID 34991564, 2022). "IL-6 and TNF-α stimulate the production of C-reactive protein by the liver, and together, they trigger the subclinical inflammation process, which in turn may result in the onset of cardiovascular diseases during adolescence." (PMID 34411143, 2021).
cardiovascular disease (continued). "Secondly, this study was only designed to examine the hs‐CRP levels but not to other inflammatory biomarkers such as IL‐6 and tumor necrosis factor α, which have also been identified as stronger predictors of clinical events in patients with cardiovascular diseases." (PMID 32458487, 2020). "The inhibition of IL‐6 signalling by Bazedoxifene and the benefits it conferred in murine pressure overload pathology might provide evidence for the potential role of Bazedoxifene in anti‐inflammatory therapy in HHD and even other cardiovascular diseases." (PMID 32164044, 2020). "IL-6 can bind the IL-6 receptor (IL-6R) and gp130, activate the Janus Kinase (JAK)-Signal Transducer and Activator of Transcription 3 (STAT3) signaling pathway, regulate inflammatory responses, and participate in the occurrence and progression of various cardiovascular diseases." (PMID 33099539, 2020). "However, ADVANCE Study performed a nested case-cohort study in 2865 patients with DM and cardiovascular diseases and showed that IL-6 levels but not Fib levels added predictive value to diabetic macrovascular events and mortality." (PMID 32192491, 2020). "Interestingly, in a recent study, a strong, independent, inverse relationship between IL-6 and RV morphology has been demonstrated also in asymptomatic individuals without documented cardiovascular disease." (PMID 31739518, 2019). "Interestingly, in a recent study, a strong, independent, inverse relationship between IL-6 and RV morphology was demonstrated in asymptomatic individuals without documented cardiovascular disease." (PMID 29875701, 2018). "Randomized controlled trials of aspirin conducted among patients with cardiovascular disease found statistically significant reductions in circulating concentrations of high-sensitivity C-reactive protein (CRP), tumor necrosis factor-alpha (TNF-α), interleukin-6 (IL-6), and thromboxane B2 (TXB2)." (PMID 28542447, 2017). "Therefore, IL-6 may be a useful biomarker for the diagnosis of PCOS and the treatment of T2DM and cardiovascular diseases in women with PCOS." (PMID 26849353, 2016). "Our data suggest that TNF-α and IL-6, but not CRP, are associated with the prevalence and severity of CKD, independent from established CKD risk factors, history of cardiovascular disease, and use of antihypertensive, antidiabetic, and lipid-lowering agents and aspirin." (PMID 26025192, 2015). "In metabolic and cardiovascular disease states, EAT reduces the production of cardioprotective adipocytokines, such as adiponectin, and induces the production of detrimental pro-inflammatory adipocytokines such as leptin, resistin, IL-6, tumor necrosis factor-α, and IL-17." (PMID 23409197, 2013). "Unlike anti-IL-1, IL-6 and TNF, no large-scale studies have assessed the role of JAK inhibitors in preventing cardiovascular disease in the general population." (PMID 38929699, 2024). "We did not evaluate high-sensitivity CRP, IL-1, IL-6, ST2, TNFα, or VEGF, all of which are considered inflammatory regulators in cardiovascular diseases." (PMID 35328412, 2022). "There is evidence from large epidemiological studies that levels of CRP, IL-6, and TNF-α are independent predictors of future cardiovascular events and mortality in subjects with and without known cardiovascular disease." (PMID 24895539, 2014).
inflammation (659 papers, 2005 to 2026). Aberrant reaction of the microcirculation characterized by movement of fluid and leukocytes from the blood into extravascular tissues. "The presence of these complexes activates B-cell responses, releases pro-inflammatory cytokines, including TNF-α and IL-6, and finally causes low-grade chronic inflammation throughout the body." (PMID 41473187, 2025). "Numerous studies have consistently shown that increased plasma levels of cytokines, including IL‐1, IL‐6, and IL‐12 are strongly associated with severe lung inflammation in individuals with COVID‐19 pneumonia, leading to an increased risk of mortality." (PMID 40177411, 2025). "Clinical studies have found that IL1 and IL6 secreted by macrophages can cause severe lung inflammation." (PMID 38992966, 2025). "According to previous reports, inflammatory cytokines such as TNF-α, IL-1β, and IL-6 are closely associated with the occurrence of intestinal inflammation." (PMID 38892496, 2024). "This process leads to the release of pro-inflammatory cytokines (TNF-α, IL-1β, IL-6), which are implicated in airway inflammation." (PMID 39000242, 2024). "Cardiovascular inflammation is closely associated with elevated inflammatory cytokines, particularly interleukin-6 (IL-6)." (PMID 37900560, 2023). "Elevated plasma levels of IL6 have been observed in TB patients with more severe disease and are associated with pulmonary inflammation and lung damage." (PMID 37834286, 2023). "Osteoblasts release IL-6 to stimulate osteoclast formation and like eotaxin-1 can be associated with bone inflammation." (PMID 37095095, 2023). "IL-6 has been identified as a key driver of TB severity and is associated with lung inflammation and lung damage." (PMID 37892223, 2023). "In this model, IL-6-deficient mice showed exaggerated lung inflammation whereas lung-specific overexpression of IL-6 reduced the disease symptoms." (PMID 35464825, 2022). "Some proteins such as C-reactive protein (CRP), serum amyloid A (SAA), procalcitonin (PCT), and interleukin-6 (IL-6) are considered to associate with the inflammation disease." (PMID 35198078, 2022). "The leading cause of CNS chronic inflammation is the release of inflammatory factors by microglia, such as interleukin-1 (IL-1), interleukin-6 (IL-6), and tumor necrosis factor-α (TNF-α)." (PMID 36570466, 2022). "Among them, those associated with systemic inflammation have been characterized and shown to express high levels of classical pro-inflammatory genes including Il6, Cxcl10, Il1b and Tnf." (PMID 34483912, 2021). "Elevated levels of interleukin 6 (IL-6) are linked with chronic intestinal inflammation and tumorigenesis." (PMID 33996591, 2021). "This is partially in contrast to an animal model of Se deficiency-induced renal inflammation, where disruption of selenoproteins led to an initiation of the NF-κB pathway with increased IL-6 and reduced IL-10 concentrations." (PMID 34203015, 2021). "Genetic ALDH2-deficient mice are prone to ethanol-induced liver inflammation and fibrosis by paracrine activation of IL-6 in Kupffer cells." (PMID 34764958, 2021). "Earlier evidences have indicated that IL-6 can promote the migration of VSMCs, which is another hallmark of progression of vascular inflammation." (PMID 34336088, 2021). "Vice versa, the correlation between IL-6 and TRAC5b was weaker, possibly because IL-6 serum levels are strongly affected by the presence of systemic inflammation that is associated with high IL-6 circulating levels." (PMID 34124067, 2021). "Only four strains induced the inflammatory cytokines TNF-α, IL-12(p70), IL-6 and IL-1β, while the remaining Lactobacillus strains downregulated these, which is again reassuring as genital inflammation has been linked to HIV and STI risk." (PMID 32497109, 2020). "IL-1 and IL-6 signaling in the spinal cord are associated with low grade chronic inflammation, and intra-thecal injection of anti-IL-6 antibodies has been shown to alleviate pathological pain." (PMID 31661848, 2019).
inflammation (continued). "Our study shows the association of serum OX40L with airway inflammation, as evidenced by its positive correlation with serum IgE, IL-6, percentages of eosinophils and neutrophils." (PMID 30890137, 2019). "Reconstitution of IL-6 deficient recipient mice with WT or IL-6 deficient basophils revealed that acute lung inflammation was restored only by WT basophils." (PMID 28134325, 2017). "In patients with LCPD, a chronic synovial inflammation is associated with a specific and sustained elevation of the pro-inflammatory cytokine interleukin-6 (IL-6) in the synovial fluid." (PMID 27045355, 2016). "CRP, TNF-α, and IL-6, which are a prominent markers of systemic chronic inflammation, have been significantly associated with poor HGS." (PMID 27078883, 2016). "The S204P variant of IL6 is associated with numerous inflammation diseases and annotated in UniProt as ‘87% loss of activity’." (PMID 26926108, 2016). "We established that IL-6 administration at the start of resuscitation is capable of completely reversing liver inflammation and is associated with increased Stat3 activation." (PMID 21738667, 2011). "Consistent with previous mouse studies, genes associated with epidermal inflammation (e.g., IL-6, IL1B, S100A7, S100A8, and S100A9) and matrix metalloproteases (MMPs) were also significantly upregulated, as were E- and L-selectin, which are required for leukocyte entry into skin." (PMID 41150413, 2025). "Studies have demonstrated that elevated levels of C-reactive protein (CRP) and interleukin-6 (IL-6) are associated with acute joint inflammation and may correlate with the severity of intra-articular soft tissue damage." (PMID 41007617, 2025). "Moreover, liver inflammation caused by EtOH is believed to be exacerbated by the pro-inflammatory cytokine IL-6, which plays a critical role in the progression of liver damage." (PMID 40291773, 2025). "Furthermore, P3 (Atractylenolide I) and P16 (8-Gingerol), linked to LAR, ZR, and GCR, modulated COX-2, RF and IL-6(G), underscoring their supportive roles in mitigating local gastric inflammation." (PMID 40717975, 2025). "In addition, the ratios of the IL-6:sIL-6R and IL-6:sIL-6R:sgp130 complexes have been reported to reflect the level of IL-6 trans-signaling and influence the risk or severity of inflammation-related diseases, such as CVE and COVID-19 infection." (PMID 38469154, 2023). "Chronic inflammation may also be derived in part from senescent cells, and elevated IL-1β and IL-6 are associated with age-related disease." (PMID 35111375, 2022). "CEA has been associated with several benign conditions, particularly chronic inflammation, and a previous study has investigated its association with widely accepted inflammatory markers, such as neutrophil/lymphocyte ratio, C-reactive protein, and IL-6." (PMID 36078939, 2022). "Furthermore, the levels of major inflammatory cytokines (TNF-α, IL-6, and IL-1β) associated with hepatic inflammation were also significantly lower." (PMID 34204055, 2021). "Elevation of TNFα and IL-6 is the hallmark of acute bowel inflammation." (PMID 34354689, 2021). "In this study, PM was hypothesized to cause IL-6-driven vascular inflammation through the coordination of TLR2 and TLR4, NADPH oxidase-derived ROS, and NF-κB signaling molecules." (PMID 34336088, 2021). "These cell changes result in enhanced IL-17 and IL-6 expression but reduced Foxp3 and IL-10 expression in the renal tissues of LN mice, which are significant risk factors for the occurrence of renal inflammation and underlying causes for developing renal damage." (PMID 31488076, 2019). "Pro-inflammatory actions of IL-6 have been demonstrated to predominantly occur via trans signaling, which is strongly associated with the development of and sustainment of intestinal inflammation in IBD." (PMID 31772929, 2019). "IL-6/STAT3 pathway has been implicated in renal inflammation and oxidative stress." (PMID 28367225, 2017).
inflammation (continued). "Furthermore, our studies demonstrate that proteases in poultry dust induce, in addition to IL-8 and IL-6, other genes implicated in lung inflammation such as IL-1β, CCL2, ICAM-1, PTGS2 and TLR4 in alveolar as well as bronchiolar epithelial cells." (PMID 27770804, 2016). "Increased liver damage and LPS stimulation may lead to hepatic production of excessive amounts of systemic IL-6, which plays a causative role in the increased pulmonary inflammation of burned intoxicated mice." (PMID 24379525, 2013). "Further studies are therefore needed to elucidate the role for IL-6 and other cytokines that may be synergistically or independently involved in the progression of various forms of human PH associated with lung inflammation." (PMID 19173740, 2009). "This extract, orally administered at 25, 50, or 100 mg/kg at 96, 72, 48, 24, and 2 h before intestinal inflammation induction, showed anti-inflammatory effects associated with increased IL-10 synthesis, reduced oxidative stress, and reduction in the pro-inflammatory cytokines IL-1β, IL-6, and TNF-α." (PMID 37242733, 2023). "Many studies have demonstrated that colonic inflammation is associated with decreased concentrations of SCFAs in the colon, resulting in decreased expression of intestinal tight junction proteins and higher expression of proinflammatory factors such as IL-1β and IL-6." (PMID 35935130, 2022). "This study provides evidence that subacute (5 days) nose-only exposure to WPS caused early pulmonary inflammation evidenced by infiltration of neutrophils and lymphocytes, increased epithelial permeability, and concentrations of proinflammatory cytokines such as TNFα and IL-6 in lung tissue." (PMID 25780090, 2015). "Disruption of this barrier is a hallmark of chronic intestinal inflammation particularly in IBDs, and is primarily driven by pro-inflammatory cytokines, such as TNF-α, IFN-γ, IL-1β, and IL-6." (PMID 42278255, 2026). "Studies have found that H2S levels are correlated with peripheral pro-inflammatory cytokines (e.g. IL-6, S100B), suggesting its potential role in systemic inflammation." (PMID 40761437, 2025). "Systemic inflammation, characterized by elevated levels of cytokines such as interleukin-6 (IL-6), tumor necrosis factor-alpha (TNF-α), and C-reactive protein (CRP), plays a pivotal role in bridging these conditions." (PMID 40218134, 2025). "The presence of low‐grade intestinal inflammation was further confirmed by an increase in mRNA levels of intestinal inflammatory cytokines, namely Tnf‐α, Il‐1β, and Il‐6, which were analyzed in whole gut tissue samples from the small intestine and colon." (PMID 40051115, 2025). "IL-6 can induce brain inflammation, potentially disrupting neural development and synaptic function." (PMID 40002751, 2025). "The expression levels of immunomodulatory cytokines (IL-10 and IL-12) and the proinflammatory cytokine (IL-6) were significantly upregulated (p < 0.01) in zebrafish subjected to DSS-induced intestinal inflammation (model group)." (PMID 40862149, 2025). "Mycobiome components like β-glucans can activate immune cells and promote pro-inflammatory cytokines (TNF-α, IL-6), exacerbating liver inflammation and bone resorption." (PMID 40235664, 2025). "Studies found that altered flora in patients with neonatal necrotizing small bowel colitis led to significant intestinal inflammation, resulting in increased expression of IL‐1, IL‐2, IL‐4, IL‐6, IL‐8, IL‐10, TNF‐α, IFN‐γ, and IL‐17 in samples." (PMID 40119640, 2025). "Recently, a research has further examined IL-6 impact on chronic respiratory diseases and respiratory inflammation." (PMID 40642273, 2025). "Macrophages play a critical role in synovial inflammation, and their interaction with FLSs results in elevated levels of IL‐6 and MMP‐3, findings that are consistent with our observations." (PMID 40985312, 2025).